ANGPTL3 (angiopoietin like 3)
Diseases named in the same sentence as ANGPTL3 in open-access papers (continued):
Sharing a sentence is not in itself a finding about the gene and the disease.
atherosclerosis (continued). "Likewise, animal models convincingly show that increased clearance of TRLs and RLPs by LPL activation (achieved by inhibition of APOC3, ANGPTL3, or ANGPTL4 action, or increased APOA5) results in protection from atherosclerosis." (PMID 32849290, 2020). "Moreover, mice treated with antisense oligonucleotides (ASOs) targeting ANGPTL3 messenger RNA (mRNA) manifested dose-dependent reductions in LDL cholesterol, TRG, atherosclerosis progression, and liver TRG content and an increase in insulin sensitivity." (PMID 30944669, 2019). "Silencing ANGPTL3 also reduced atherosclerosis in several models of atherosclerosis in non-diabetic mice, but nothing is known about whether reducing ANGPTL3 would rescue diabetes-accelerated atherosclerosis or foam cell formation." (PMID 37378396, 2023). "In addition to inclisiran, it appears that ANGPTL3, APOCIII, and Lp(a)-targeted therapies are very attractive candidates that protect against atherosclerosis, and a whole new avenue will be launched in the treatment of CVD risk factors with RNAi-based medicines in the near future." (PMID 34146172, 2021). "ROC curve analyses indicated that ANGPTL3 concentrations above 30.5 ng/mL can predict atherosclerosis with a sensitivity of 71.2% and specificity of 75.3%, and that ANGPTL4 levels below 497.5 ng/mL can predict atherosclerosis with a sensitivity of 63.9% and specificity of 74.5%." (PMID 34742313, 2021). "However, to date, the effect of pharmacological inhibition of PCSK9 and ANGPTL3 on regression of atherosclerosis has not been investigated." (PMID 31843957, 2020). "Conversely to the FLDs from other angiopoietins that bind to endothelial cells via Tie receptors (Tie1 and Tie2), ANGPTL3’s FLD binds to integrin αVβ3; while this interaction has a proven role in the case of renal damage, a more puzzling scenario is depicted for its importance in atherosclerosis." (PMID 30011918, 2018). "Additionally, in humans, carriers with homozygous LOF mutations in ANGPTL3 have lower plasma LDL-C, TG levels and lower risk of atherosclerosis compared to the non-carriers." (PMID 29334984, 2018). "As the study showed, the concentration of ANGPTL3 was significantly higher and that of ANGPTL4 was obviously lower in the atherosclerosis group than in the nonstenosis group." (PMID 34742313, 2021). "So, it is a concern that ANGPTL3 inhibition reduces HDL-C cholesterol levels, while reducing LDL levels, and thus may not be an ideal treatment for HoFH to reduce progression of atherosclerosis and cardiovascular complications." (PMID 34146172, 2021).
hypertriglyceridemia (49 papers, 2014 to 2025). A laboratory test result indicating elevated triglyceride concentration in the blood. "Currently, ANGPTL3 has emerged as a highly promising drug target for hypertriglyceridemia and associated cardiovascular diseases." (PMID 37634084, 2024). "Meanwhile, mice with ANGPTL3 and ANGPTL4 deficiency had severe hypertriglyceridemia while mice with ANGPTL3 overexpression had hyperlipidemia." (PMID 37170504, 2023). "Consistently, it was observed that the overexpression of ANGPTL3 in mice causes hypertriglyceridemia, whereas the loss-of-function mutation of ANGPTL3 in humans causes familial combined hypolipidemia (FHBL2, OMIM #605019)." (PMID 35454174, 2022). "Monoclonal antibodies and antisense oligonucleotides that target ANGPTL3, and 4 are potentially an efficient therapeutic strategy for cardiovascular risk reduction in hypertriglyceridemia, especially in patients with FHTG." (PMID 33588820, 2021). "In homozygotes, the complete Angptl3 deficiency was associated with a highly reduced postprandial hypertriglyceridemia, probably due to an accelerated catabolism of intestinal derived TG-rich lipoproteins (chylomicrons) secondary to the increased LPL activity." (PMID 29752428, 2019). "Moving along the gradient, individuals with a high PRS but without major pathogenic variants represent a polygenic form of hypertriglyceridemia that responds partially to ANGPTL3 inhibition with evinacumab, reflecting preserved but inefficient lipolytic function." (PMID 41300829, 2025). "By virtue of ANGPTL3’s crucial role in this process and the findings of loss of function studies in humans and animals, ANGPTL3 inhibitors may play a therapeutic role in the treatment of hypertriglyceridemia." (PMID 39274442, 2024). "In females, ANGPTL8 was found to be of very good diagnostic ability in identifying subjects with hypertriglyceridemia (AUC = 0.83), similar to that of remnant-C and sdLDL-C (AUC = 0.87), though the power of discrimination of ANGPTL3 was much lower (AUC = 0.71)." (PMID 34959891, 2021). "Similarly, we were also able to ascertain that a likely mechanism by which LXR agonists cause hypertriglyceridemia is through stimulation of hepatic ANGPTL3/8 secretion." (PMID 33762177, 2021). "The role leptin on ANGPTL3 expression and plasma level in humans was recently documented in a study conducted in patients with generalized lipodystrophy, a leptin deficient condition associated with hypertriglyceridemia." (PMID 29752428, 2019). "The importance of ANGPTL3 in this process, as well as findings from animal and human loss of function investigations, have shown the potential involvement of ANGPTL3 inhibitors as a treatment option for hypertriglyceridemia, as we discuss later in section 10 of this review." (PMID 38303975, 2023). "Clinically, first-in-human and hypertriglyceridemia trials with the ANGPTL3 monoclonal antibody evinacumab demonstrated dose-dependent TG reductions with favorable safety." (PMID 41561063, 2025). "ANGPTL3, a protein primarily expressed in the liver, is commonly targeted by inhibitors as an effective strategy for treating hypertriglyceridemia and other lipid metabolism disorders." (PMID 38820493, 2024). "We suspect that the ANGPTL3/8 mAb, by increasing intracapillary LPL levels, will be highly effective in treating hypertriglyceridemia in patients with APOA5 deficiency." (PMID 37824203, 2023). "Vupanorsen, an inhibitor of ANGPTL3, was also studied in a recent analysis conducted on four patients with FPLD (two with pathogenic variants in the LMNA gene), severe hypertriglyceridaemia and hepatic steatosis." (PMID 36899861, 2023). "Previous work has showed that siRNA treatment of Angptl3 reduced the proteinuria and hypertriglyceridemia in a rat model with puromycin-induced NS, indicating that ANGPLT3 is a potential target for podocytopathy." (PMID 36229446, 2022).
hypertriglyceridemia (continued). "On the contrary, in males, ANGPTL3 was a better discriminator between subjects with hypertriglyceridemia (AUC = 0.78) than in females (AUC = 0.71)." (PMID 34959891, 2021). "The inhibition of ANGPTL3 is a promising pharmacological target for the prevention of coronary artery disease in hypertriglyceridemia especially in persons with FHTG in which the control of triglycerides levels is a challenge." (PMID 33588820, 2021). "As already discussed, the inhibition of ANGPTL3 and apoCIII are other promising therapeutic approaches to hypertriglyceridemia targeting these proteins with ribonucleic acid (RNA) interfering therapies are presently being exploited." (PMID 34067469, 2021). "Contrary to this, ANGPTL3 was a better discriminator of hypertriglyceridemia (AUC = 0.78) in male subjects." (PMID 34959891, 2021). "We focused on the observation that ANGPTL3 is required by ANGPTL8 to inhibit LPL and the co-expression of ANGPTL3 and ANGPTL8 induces more pronounced hypertriglyceridemia than the overexpression of ANGPTL3 alone." (PMID 34293055, 2021). "Phase I trials with weekly administration of 60 mg of IONIS-ANGPTL3-LRX to healthy volunteers with hypertriglyceridemia resulted in reductions of ANGPTL3 (85%), TG (50%), LDL cholesterol (33%) and HDL cholesterol (27%)." (PMID 31340607, 2019). "Thus, the finding of elevated ANGPTL3 levels in patients with lipodystrophy and their reduction following leptin treatment is consistent with the results obtained in leptin deficient mice and suggests that ANGPTL3 may contribute to hypertriglyceridemia in leptin deficient states." (PMID 29752428, 2019). "Two known negative regulators of ANGPTL3 transcription are insulin and leptin, which is a relevant issue in hypertriglyceridemia and hyperfattyacidemia in diabetic patients." (PMID 30011918, 2018). "KK/San mice and wild-type mice treated with recombinant ANGPTL3 show a rescue in the low-TG phenotype in the former and hypertriglyceridemia due to ANGPTL3-mediated inhibition of LPL in the latter." (PMID 30011918, 2018). "Taken together, these evidences reveal an intuitively mechanism of Angptl3/ Angptl8-mediated hypertriglyceridemia induced by LXRs." (PMID 27845381, 2016). "LXRs also regulate the expression of angiopoietin-like protein 3 (Angptl3), leading to hypertriglyceridemia via inhibition of LPL activity and activation of lipolysis in adipocytes." (PMID 24872814, 2014). "After considering these reports, and in light of our previous finding that insulin can stimulate secretion of ANGPTL3/8 from hepatocytes, we hypothesized that LXR agonists might cause hypertriglyceridemia by stimulating hepatic secretion of ANGPTL3/8." (PMID 33762177, 2021). "ANGPTL3 decreases LPL activity; thus, animals overexpressing ANGPTL3 manifest hypertriglyceridemia." (PMID 30944669, 2019). "Polyunsaturated fatty acids (PUFAs) have beneficial effects on hypertriglyceridemia although their effect on angiopoietin-like proteins (ANGPTLs), specifically ANGPTL3, ANGPTL4 and ANGPTL8 is unknown." (PMID 32153916, 2019). "The link between ANGPTL3 and plasma lipoprotein metabolism emerged from the identification of the KK/San mouse strain, a mutant strain derived from a colony of KK mice characterized by diabetes, obesity and hypertriglyceridemia." (PMID 29752428, 2019). "Furthermore, Angptl3 overexpression, either by adenovirus infection or by recombinant protein i.v. injection, rescues the low TG phenotypes of KK/San mice, and leads to hypertriglyceridaemia in wild-type mice." (PMID 27053679, 2016). "Plasma TAG levels are unchanged in mice expressing ANGPTL3 alone, whereas coexpression with betatrophin results in hypertriglyceridemia despite a reduction in circulating ANGPTL3, suggesting betatrophin may regulate lipid metabolism by activating ANGPTL3." (PMID 26819617, 2015).
hypertriglyceridemia (continued). "APOC3 and ANGPTL3 inhibitors provide potent triglyceride reduction in monogenic and refractory forms, while metabolic agents such as GLP-1 receptor agonists target the hepatic and insulin-resistant components characteristic of polygenic or MASLD-associated hypertriglyceridemia." (PMID 41300829, 2025). "ANGPTL3 inhibitors may play a therapeutic role in the treatment of hypertriglyceridemia." (PMID 39274442, 2024). "APOA5 deficiency leads to hypertriglyceridemia, which may reflect its role in the efficient association of TRL with LPL or GPIHBP1 on endothelial cells, possibly because APOA5 interferes with an inhibitory effect of ANGPTL3/ANGPTL8 on this association." (PMID 34981790, 2022). "We conclude that ANGPTL8 is specific for the regulation of TG-rich lipoproteins through the LPL pathway and that therapeutically targeting ANGPTL8 for the treatment of hypertriglyceridemia or cardiovascular disease may have different outcomes than targeting ANGPTL3." (PMID 34461133, 2021). "Therefore, it seems likely that the hypertriglyceridemia observed with LXR agonists could be due at least in part to LXR agonist-induced hepatic secretion of ANGPTL3/8." (PMID 33762177, 2021). "A previous study has demonstrated that the siRNA-mediated knockdown of liver ANGPTL3 relieved its inhibitory effect on LPL and significantly reduced hypertriglyceridemia and oxidative stress in nephrotic rats." (PMID 39088466, 2024). "The ANGPTL3 gene is a direct target of LXR, and overexpression of hepatic ANGPTL3 via activation of the LXR-dependent pathway leads to TG accumulation in the liver and hypertriglyceridemia." (PMID 36293338, 2022). "Taken together, our results shed light on a novel intersection of ApoA5 and the ANGPTL3/4/8 family of proteins in the regulation of TG metabolism and also provide a possible explanation for LXR agonist–induced hypertriglyceridemia." (PMID 33762177, 2021). "Together, these results reveal a novel intersection of ApoA5 and ANGPTL3/8 in the regulation of TG metabolism and provide a possible explanation for LXR agonist-induced hypertriglyceridemia." (PMID 33762177, 2021). "Since ANGPTL3, ANGPTL4, and ANGPTL8 are all LPL inhibitors, the absence of anyone of them would break the balance of triglyceride metabolism in turn would lead to hypotriglyceridemia or hypertriglyceridemia." (PMID 37170504, 2023). "Related studies have confirmed that expression of ANGPTL8 in ANGPTL3 knockout mice failed to promote hypertriglyceridemia." (PMID 37170504, 2023). "This further supports our findings, as high ANGPTL8 levels are thought to contribute to hypertriglyceridemia rather than high ANGPTL3 levels." (PMID 34293055, 2021). "Both ANGPTL3 and ANGPTL8 interact as regulators of LPL activity, and both are targets for pharmacotherapeutic agents currently undergoing testing as potentially effective drugs in the treatment of hypertriglyceridemia." (PMID 34959891, 2021). "In contrast, in males, ANGPTL3 was proved a good discriminator between subjects with hypertriglyceridemia and those without (AUC = 0.78), with remnant-C presenting excellent discrimination (AUC = 0.92)." (PMID 34959891, 2021). "A high-cholesterol diet induces ANGPTL3 hepatic expression in mice by activating LXRs, leading to hypertriglyceridemia, an effect that is not observed in ANGPTL3-null mice." (PMID 30011918, 2018). "Of note, overexpression of Angptl3 alone does not alter the levels of circulating TG, whereas co-expressing it with Angptl8 results in hypertriglyceridemia in mice." (PMID 27845381, 2016).
hypertriglyceridemia (continued). "The direct implication of the ANGPTL3-4-8 model is that when ANGPTL8 is increased, LPL activity will be suppressed in the heart and skeletal muscle, resulting in accumulation of TG in the circulation (hypertriglyceridaemia)." (PMID 27053679, 2016). "Angiopoietin-like protein 3 (ANGPTL3) is a secretory protein known to inhibit lipoprotein lipase, the enzyme that degrades circulating triglycerides in the capillaries of muscle and adipose tissue, and its inhibition leads to hypertriglyceridemia, which enables atherosclerotic plaque formation." (PMID 36975891, 2023). "With the intake of a high-fructose or high-sucrose diet, Fgf21 and Angptl3, rather than Angptl8, may be better targets for the improvement of hypertriglyceridemia." (PMID 30405056, 2018). "Furthermore, overexpression of ANGPTL8 in ANGPTL3-knockout mice failed to promote hypertriglyceridemia." (PMID 26739706, 2016). "Among predictors of hypertriglyceridemia, ANGPTL8 was the best positive predictor in women, whereas the effect of ANGPTL3, though significant, was very low irrespective of gender." (PMID 34959891, 2021). "Although plasma TG levels did not change in mice overexpressing ANGPTL3 alone, co-overexpression of ANGPTL3 and ANGPTL8 resulted in hypertriglyceridemia." (PMID 26739706, 2016). "These patients were found to have increased plasma levels of ANGPTL3 (but not plasma levels of ANGPTL4), suggesting the possibility that hypertriglyceridemia might be the result of ANGPTL3 mediated inhibition of LPL." (PMID 29752428, 2019). "However, in ANGPTL3-null mice, an LXR agonist could not induce hypertriglyceridemia but did induce the accumulation of TGs in the liver." (PMID 34298929, 2021).
coronary artery disease (48 papers, 2016 to 2025). "Several publications have reported that ANGPTL3 deficiency protects against coronary artery disease (CAD)." (PMID 36614969, 2022). "Conducting mendelian randomisation (MR) provided strong evidence of an effect of drug-based genetic scores on coronary artery disease (CAD) risk with the exception of ANGPTL3." (PMID 35213538, 2022). "The genetics and mechanism of ANGPTL3 inhibition clearly illustrate the multiple pathways of lipoprotein lowering and coronary disease risk reduction associated with increasing genetic variants of LPL." (PMID 36552028, 2022). "Mutations resulting in the loss of ANGPTL3 function are associated with lower plasma triglycerides and protection from coronary artery disease (CAD)." (PMID 33482195, 2021). "Although heterozygous ANGPTL3 loss-of-function variants were associated with a 41% lower odds of coronary artery disease, the median level of LDL-C in the heterozygous variants was approximately 112 mg/dL." (PMID 33255270, 2020). "Angiopoietin-like protein 3 (ANGPTL3) plays a pivotal role in lipid metabolism and angiogenesis, and there is growing interest regarding the association between ANGPTL3 and coronary artery disease (CAD)." (PMID 32280540, 2020). "A previous study reported that ANGPTL3 deficiency reduced the risk of coronary heart disease in humans." (PMID 29940978, 2018). "A study examining the relationship between ANGPTL3 loss-of-function variants and coronary artery disease in 58,355 adults reported that the presence of an ANGPTL3 loss-of-function variant was associated with a 41% lower odds of CAD (OR 0.59; 95% CI 0.41–0.85)." (PMID 30090066, 2018). "For a given genetic difference in LDL-C level, the association of ANGPTL3 variants with lower coronary disease risk was stronger than that of the LDL-C–lowering genetic score (P for heterogeneity = .009) (eFigure 7 and eTable 8 in the Supplement)." (PMID 30326043, 2018). "ANGPTL3 is therefore a potential therapeutic target to treat combined hyperlipidemia, a major risk factor for atherosclerotic coronary heart disease." (PMID 26754661, 2016). "ANGPTL3 is a hepatokine that inhibits lipoprotein and endothelial lipases, and human loss-of-function and pharmacologic antagonism lower triglycerides and low-density lipoprotein and are associated with reduced coronary disease risk." (PMID 41282674, 2025). "Genetic inactivation of ANGPTL3 is associated with a lower risk of ischemic heart disease." (PMID 33716107, 2021). "ANGPTL3 deficiency has been linked to protection from coronary artery disease." (PMID 34422408, 2021). "In addition, the LOF variants of Angptl3 were found to be associated with a 39% reduction of coronary artery disease (CAD)." (PMID 29752428, 2019). "For a given genetic difference in LDL-C, the association with lower risk of coronary disease conveyed by rare loss-of-function variants in ANGPTL3, which are associated with lower LDL-C levels and enhanced LPL lipolysis, was greater than that conveyed by other LDL-C–lowering genetic mechanisms." (PMID 30326043, 2018). "It is reported that ANGPTL3 deficiency reduces the risk of coronary heart disease in humans." (PMID 30021605, 2018). "More recently, the discovery of loss-of-function variants in ANGPTL3 that lower blood triglyceride levels and protect against coronary artery disease has suggested that ANGPTL3 inhibition may reduce blood triglyceride levels and risk of coronary artery disease." (PMID 29691411, 2018). "ANGPTL3 is an endothelial lipase inhibitor secreted from the liver that inhibits lipoprotein lipase, important for overall lipid metabolism, regulation, and coronary artery disease." (PMID 40924496, 2025). "They had half the ANGPTL3 levels of other subjects and a 39% lower probability of coronary artery disease." (PMID 36552028, 2022). "Heterozygous and homozygous carriers of ANGPTL3 LOF mutations have reduced risk for T2DM and coronary heart disease." (PMID 30944669, 2019).